HIF1A (hypoxia inducible factor 1 subunit alpha)
Diseases named in the same sentence as HIF1A in open-access papers (continued):
Sharing a sentence is not in itself a finding about the gene and the disease.
cancer (continued). "In addition, HIF-1α has shown potential therapeutic effects in cancer and fracture repair." (PMID 32587244, 2020). "Besides this oxygen-dependent regulation of HIF-1α, reactive oxygen species (ROS) and nitric oxide (NO), crucial in tumorigenesis and particularly high in cancer cells, also contribute to the stabilization of HIF-1α by inhibiting PHDs activity under both hypoxic and normoxic conditions." (PMID 32286485, 2020). "Moreover, the fact that most of the glycolysis-related genes are regulated by HIF-1α could explain why hypoxia stimulation induces CSC traits in differentiated cancer cells in many tumors." (PMID 32998263, 2020). "Therefore, HIF-1α/MDR1 signaling pathway would be a target for cancer drug resistance therapy." (PMID 31402869, 2019). "The hypoxia-induced transcription factor HIF-1α is linked to the Warburg effect through its upregulation of glucose transporters, elevated expression of enzymes involved in glycolysis, and inhibition of oxidative phosphorylation, resulting in HIF-1α-mediated glycolysis in cancer cells." (PMID 31552162, 2019). "In the present study, we hypothesized that TQ is a potential anti-cancer drug targeting HIF-1α." (PMID 30832444, 2019). "Moreover, HIF‐1α was shown to induce EMT in many types of cancer tissues." (PMID 30653763, 2019). "Therefore, hypoxia-selective growth inhibition of cancer cells by treatment with compounds 1 and 2 may result from decreased HIF-1α accumulation under hypoxic conditions." (PMID 30857246, 2019). "Given the importance of HIF1A for cancer pathobiology, the pseudohypoxia concept could shed light on the longstanding mystery of the Warburg effect and accelerate better understanding of the diverse phenomena seen in a variety of cancers." (PMID 30844107, 2019). "In addition to acting as an oncogene in many cases, YAP may complex with other transcription factors to regulate cancer biology including HIF-1α, which controls cancer cells stemness following radiotherapy in an oxygen dependent or independent manner." (PMID 31558702, 2019). "However, it is not yet clear whether TQ reduces hypoxia-inducible factor-1α (HIF-1α) expression in hypoxic cancer cells." (PMID 30832444, 2019). "Thus, NRF2 and miR-181c could be effective targets to counteract HIF-1α-orchestrated metabolic adaptation of hypoxic cancer cells." (PMID 31078780, 2019). "In addition, HIF‐1α was shown to induce EMT in many types of cancer tissues." (PMID 30653763, 2019). "Moreover, HIF-1α stabilized by hypoxia microenvironment is also able to activate the expression of PD-L1 by binding of HIF to a specific hypoxic response element in the promoter of PD-L1 in cancer cells." (PMID 31122265, 2019). "Thus, PD-L1 inhibition as well as blocking HIF-1α might represent a promising approach to enhance cancer immunotherapy." (PMID 31083487, 2019). "Thus, extensive studies have demonstrated that targeting HIF-1α could be a promising anti-cancer therapeutic strategy." (PMID 30832444, 2019). "Therefore, the mechanisms that NEDD4L- and HIF-1α- mediated regulation of GC progression need to be explored further, which may ultimately promote the development of new anti-cancer strategies." (PMID 31673244, 2019). "Furthermore, it has been reported that HIF-1α increases 5-FU resistance in cancer cells in hypoxia." (PMID 31491980, 2019). "Moreover, in hypoxic stress, cancer cells enhance lipid synthesis that is important for membrane biosynthesis and energy storage for cell survival and proliferation, being induced this hypoxia lipogenic phenotype via dependent- and HIF1α-independent pathways." (PMID 31354511, 2019). "In addition, linc00152 might enhance the invasion and migration capacities of cancer cells by sponging miR-138 and upregulating hypoxia-inducible factor-1α (HIF-1α) expression." (PMID 31896236, 2019).
cancer (continued). "Cancer cells arriving from primary sites in the GI tract, the breast, and the lung must undergo metabolic changes through the regulation of hypoxia-induced transcription factors (e.g., HIF-1α and c-Myc), which will help develop low-oxygen tolerance to survive this hypoxic environment." (PMID 31450598, 2019). "Interestingly, the association between HIF-1α and ARNT can also be inhibited by interaction of HIF-1α with MgcRacGAP (male germ cell RacGTPase Activating Protein) in cancer cells or after treatment of human bronchial smooth muscle cells with the proinflammatory factor TNF-α." (PMID 30832409, 2019). "Thus, the inhibition of HIF-1α expression or activity may offer a therapeutic potential against infections, inflammation and cancer progression." (PMID 30609861, 2019). "Therefore, targeting NRF2/miR-181c could be an effective strategy to counteract HIF-1α-orchestrated metabolic adaptation of hypoxic cancer cells." (PMID 31078780, 2019). "Interestingly, topoisomerase I inhibitors were observed to inhibit the translation of HIF1A and may therefore function in part by this mechanism in the case of cancers where this factor plays a significant role." (PMID 31067678, 2019). "However, carcinoma cells with nuclear HIF-1α or membranous CAIX staining could be observed in SQ20B xenografts harvested from non-treated mice." (PMID 31640284, 2019). "A previous study confirmed that HIF1α can activate the transcription of target genes that regulate various biological processes, including cell proliferation, glucose metabolism, and pH regulation, playing a vital role in the adaptation of cancer cells to hypoxic conditions." (PMID 29688867, 2018). "HIF1α activation enables recruitment of blood vessels to the rudimentary neoplasm (so called angiogenic switch) and shifts the energy metabolism toward oxygen-independent glycolysis (so called glycolytic switch), with both these features being regarded as key properties of cancer." (PMID 30534534, 2018). "Lactate also upregulates vascular endothelial growth factor and hypoxia-inducible factor 1 alpha (HIF-1α), an oxygen-sensitive transcription factor that positively regulates glycolysis, particularly in collaboration with c-Myc (Myc), which is deregulated in the majority of human cancers." (PMID 29706933, 2018). "However, treating hypoxic tumors with NO may be challenging, as NO was also demonstrated to enhance HIF-1α levels and activity in cultured human cancer cells." (PMID 30082427, 2018). "In addition, HIF-1α inactivation decreased the expression of inducible nitric oxide synthase (iNOS), further decreasing the amount of nitric oxide (NO) and leading to less permeable ECs for cancer cell migration." (PMID 29896451, 2018). "Thus, hypoxic cancer cells evade innate immunity through HIF-1α-dependent expression of CD47." (PMID 30061885, 2018). "Therefore, HIF-1α may be an ideal target for shutting down both FA metabolism and stemness signaling in cancer cells, and ultimately preventing the conversion from cancer cells to CSCs/TICs/DTPs." (PMID 29996946, 2018). "Thus, our results link the IFN-α-mediated inflammatory response to the HIF-1α expression and to tumorigenic and metastasis progression, providing evidence for a novel metastasis-promoting mechanism of cancer when situates in inflammatory hypoxia microenvironments." (PMID 29587825, 2018). "In some cancers, HIF1a stabilization may be promoted by VHL promoter hypermethylation." (PMID 28931650, 2017).
cancer (continued). "Endogenous JMJD2C has been found to physically interact with HIF-1α, which was involved in multi-steps of cancer progression, including cell proliferation, angiogenesis, invasion and metastasis, as well as the glucose and energy metabolism in human cancer cells." (PMID 29207681, 2017). "In particular, CAIX, a membrane bound isoform of CA transcriptionally regulated by HIF-1α, induces extracellular acidification catalyzing the CO2 hydration and its overexpression is associated with increased metastasis and poor patients survival in several cancers." (PMID 28352611, 2017). "Thus, if the Warburg effect decreases following an inhibition of cancer-induced HIF-1α, cancer cachexia may be reversed at least to some extent." (PMID 29152137, 2017). "Previously, the phenethyl ester of caffeic acid (CAPE) was reported to modulate PDK1 at the level of its gene expression in a context of induction of hypoxia via hypoxia-inducible factor 1α (HIF1α), which might have influenced cancer cell adaptation to metabolic demands." (PMID 28230778, 2017). "Therefore, these pathways regulating HIF-1α are a potential therapeutic target for cancer." (PMID 28165392, 2017). "Moreover, the promotive effect of hypoxia on cancer cell proliferation and invasion could be partly restored after either miR-142 overexpression or HIF-1α knockdown." (PMID 28069592, 2017). "The mechanisms may include cancer stem cells, hypoxia [e.g., Hypoxia-inducible factor 1α; (HIF-1α)], human papillomavirus (HPV), and signal transduction pathways [e.g., the signal transducer and activator of transcription 3 (STAT3), phosphoinositide-3 kinase (PI3K)/Akt]." (PMID 27823965, 2017). "However, whether AE-AS inhibits hypoxia-evoked cancer angiogenesis and the involvement of HIF-1α-regulated processes remain unknown." (PMID 28710377, 2017). "Moreover, HIF-1α mRNA and protein are overexpressed in human cancer and leukemic stem cells." (PMID 27903985, 2017). "Here, we tested our hypothesis that knockdown of HIF-1α by siRNA gene therapy delivered by the attenuated Salmonella Typhi Ty21a is a promising strategy to increase the sensitivity of PCa to DDP from the perspective of targeting cancer-specific metabolism." (PMID 28790395, 2017). "The HIF1A gene encodes the HIF-1α protein (hypoxia-inducible factor 1), an oxygen dependent subunit and master transcriptional regulator of the mammalian cell response to oxygen deprivation, and is therefore important in both the cardiovascular and cancer fields." (PMID 28381629, 2017). "Therefore, NDRG3 as well as HIF-1α may be targets controlling the aggressive behaviors of hypoxic cancer cells." (PMID 27447861, 2016). "Because docetaxel induces the JNK2/PHD1 signaling pathway and increases HIF-1α degradation, we investigated whether blocking the JNK2/PHD1 signaling pathway prevents docetaxel-mediated cancer cell death under hypoxic conditions through inhibition of HIF-1α degradation." (PMID 27263528, 2016). "Therefore, HIF-1α inhibition is a promising and effective strategy for the treatment of cancers." (PMID 27754413, 2016). "We next examined whether Compound 7 reduced HIF-1α accumulation in various cancer cell lines." (PMID 27611801, 2016). "HIF-1α, induced by hypoxia, is regarded as the key transcription factor in downstream regulation, and activates a signaling transduction network including cell cycle, cell apoptosis and metastasis which drives the adaptation of cancer cells under hypoxic conditions to a more aggressive phenotype." (PMID 27016414, 2016). "We would like to argue that patients with HIF-1α overexpressing cancer and a high plasma level of Hsp90α could benefit from treatments such as the monoclonal antibody 1G6-D7, that selectively targets the secreted Hsp90α - a critical downstream effector of HIF-1α." (PMID 26846992, 2016).
cancer (continued). "However, determination of common factors involved in resistance to chemotherapy or radiotherapy such as HIF-1α could help oncologists to select an appropriate (combinatorial) therapy for cases with advanced cancers." (PMID 26862532, 2016). "Therefore, Daxx may be a potential therapeutic target for strategies designed to inhibit cancer metastasis driven by hypoxia and the HIF-1α pathway." (PMID 28004751, 2016). "Therefore elevated levels of both metabolites stabilize HIF1α, activating glycolysis in cancers." (PMID 27358718, 2016). "Besides this function, mitochondrial cholesterol accumulation may indirectly contribute to the metabolic changes of cancer cells by impairing mitochondria function and activation of survival programs turned on by HIF1α activation." (PMID 27455839, 2016). "Therefore, it is speculated that pyruvate oxidation through PDH is decreased in M(LPS) macrophages, a similar phenotype to cancer cells with stabilized HIF1α." (PMID 26679997, 2016). "Hence, targeting HIF1α is a potential therapy for cancer treatment." (PMID 27825361, 2016). "We find stromal HIF-1α expression to be highly significantly associate with SLC2A1 mRNA expression where the corresponding protein, GLUT1, is known as an important protein facilitating increased glycolysis on which the cancer cells and hypoxic cells are dependent." (PMID 27634881, 2016). "ZFP91 may serve as a driver gene to activate HIF-1α transcription in the development of cancer." (PMID 27144516, 2016). "Subsequently, HIF-1α may create “pseudo-hypoxia” by enhancing the transcription of a series of hypoxia-related genes such as Arg-1, which can metabolize arginine to provide the substrates for cancer cell proliferation." (PMID 26474279, 2015). "Indeed, HIF-1α is overexpressed in a variety of human cancers compared to normal tissues." (PMID 26610526, 2015). "Therefore, HPV may, indirectly through HIF-1α, have a role in the metabolic reprogramming of cancer cells, by stimulating, among other HIF-1α targets, MCT4 and CAIX, key proteins in the hyperglycolytic and acid-resistant phenotype of cancer cells." (PMID 26525902, 2015). "Similarly, a novel topo II inhibitor MFTZ-1 reduced HIF-1α accumulation driven by hypoxia or growth factors in human cancer cells, possibly through the inhibition of PI3K-Akt and MAPK pathways, eliciting anti-angiogenesis independently of its topo II inhibition." (PMID 26649750, 2015). "Hence, there exists a close link between EMT and HIF-1α expression in cancer with the mechanisms unknown." (PMID 26057751, 2015). "Therefore, necrotic cell death and apoptosis of cancer cells may be induced by the deletion of HIF-1α." (PMID 26017562, 2015). "Thus, HIF-1α is considered a promising target for cancer treatment." (PMID 26469226, 2015). "Moreover, HIF1α is a key regulator of hypoxic response in cancer." (PMID 26590320, 2015). "Moreover, we established the effects of CBF treatment under both hypoxic and normoxic conditions, as several of these ion pump inhibitors, including digoxin and ouabain, have been shown to play an anti-cancer role by diminishing hypoxia-inducible factor 1 alpha (HIF-1α) expression." (PMID 26134506, 2015). "The cancer promoting effect of such mutations was supported when it was shown that inducing mitochondrial dysfunction by knocking down two subunits, GRIM-19 or NDUFS3 of Complex I increased ROS production, HIF-1α and EMT markers, promoting an invasive and more metastatic phenotype." (PMID 25688484, 2015). "Gene ontology annotation of genes neighboring HIF-binding sites revealed a strong bias towards cancer association for HIF-binding genes, which was stronger for HIF-2α than HIF-1α associated transcripts, in keeping with the pro- and anti-tumorigenic actions of HIF-2α and HIF-1α in this setting." (PMID 26262842, 2015). "Thus, HIF-1α is an established target for the development of cancer therapeutics." (PMID 26528854, 2015).
cancer (continued). "Some recent evidences suggest that inhibition of mitochondrial respiration leads to accumulation of glycolytic end products like pyruvate and lactate which could dramatically increase HIF1α accumulation in cancer cells by inhibiting the prolyl hydroxylase enzyme activity." (PMID 25925410, 2015). "Hence, this double-edged sword of HIF1A should be carefully manipulated in cancer therapies." (PMID 26432836, 2015). "Furthermore, as hypoxia has well-documented effects on cancer malignancy and resistance to chemotherapy, hypoxia inducible factor 1α (HIF-1α), a downstream protein of mTORC1 that regulates the expression of P-gp and MRP1, has emerged as an attractive target for cancer therapy." (PMID 25310259, 2014). "Instead, we found that Celastrol could induce HIF-1α protein accumulation in multiple cancer cell lines in an oxygen-independent manner and that the enhanced HIF-1α protein entered the nucleus and promoted the transcription of the HIF-1 target genes VEGF and Glut-1." (PMID 25383959, 2014). "Thus, the PH domain of PLD1 may be useful in development of effective anti- HIF-1α peptide therapeutics against cancers." (PMID 25361009, 2014). "Consistent with this hypothesis, the induction of CXCR4 by hypoxia has been reported to depend on both the activation of HIF-1α and the stabilization of the transcript in cancer cells, which is paralleled by an increase in the chemotactic responsiveness to its specific ligand, SDF-1α." (PMID 25396735, 2014). "Moreover, SDHB was decreased in CoCl2-treated cancer cells accompanied by HIF-1α up-regulation." (PMID 25491408, 2014). "It is not known whether 15-LOX-1 loss in cancer cells affects cancer cell response to hypoxia, including HIF-1α and angiogenesis upregulation and the development of a metastatic phenotype." (PMID 24634093, 2014). "In cancer cells, the corresponding mechanisms associated with NIR dye uptake could involve the aberrant activation of HIF-1α and its transcription factor activity, resulting in direct induction of OATPs through binding to hypoxia-response elements within OATP promoters." (PMID 25361418, 2014). "Therefore, inhibition of HIF-1α activity represents an attractive strategy for cancer treatment." (PMID 24925080, 2014). "In this study, we reported for the first time that Celastrol could induce HIF-1α protein accumulation in multiple cancer cell lines in an oxygen-independent manner and that the enhanced HIF-1α protein entered the nucleus and promoted the transcription of the HIF-1 target genes VEGF and Glut-1." (PMID 25383959, 2014). "In hypoxia, cells typically demonstrate increased activity of HIF-1α, a transcription factor that binds to hypoxia-response elements to activate the expression of genes that regulate proliferation, angiogenesis, metabolism, apoptosis and the maintenance of an undifferentiated state in cancer cells." (PMID 25541962, 2014). "Additionally, 4-HPA, a water-soluble small molecular compound, could be a potential agent for the diseases with hypoxia-induced inflammation or edema and some carcinomas of which hypoxia-induced HIF-1α promoted the progress." (PMID 25050781, 2014). "HIF1α/HIF2α imbalance in cancer cells might be important for RCC growth and metastasis." (PMID 23442546, 2013). "Therefore we hypothesized that HIF-1α might play a central role in modulating the cancer cell bioenergetics in response to reducing OT." (PMID 23840849, 2013).